USP32P3 (ubiquitin specific peptidase 32 pseudogene 3)
Gene: Transcribed unprocessed pseudogene on chromosome 17 (20,424,589 to 20,431,008, forward strand). Ensembl gene ENSG00000189423.
Diseases named in the same sentence as USP32P3 in open-access papers:
USP32P3 is named in the same sentence as 2 diseases in open-access papers, as found by Europe PMC text mining. Sharing a sentence is not in itself a finding about the gene and the disease. The quoted sentences say what the papers report.
cancer (1 paper, 2021). A tumor composed of atypical neoplastic, often pleomorphic cells that invade other tissues. "More importantly, no study has reported the roles of LINC00609, AC012615.1, and USP32P3 in cancers." (PMID 34880375, 2021).
USP32P3 also shares sentences with these, for which no sentence is quoted: glioma (1 paper).